TSLIG3A (tRNA splicing ligase complex subunit 3A)
Description:
Positively stimulates PRMT1-induced protein arginine methylation. Involved in skeletal homeostasis (By similarity). Positively regulates lysosome peripheral distribution and ruffled border formation in osteoclasts (By similarity).
Synonyms: FAM98A; DKFZP564F0522; RASGRP3-AS1
Tractability: PROTAC: ubiquitination databases record sites on it; its protein half-life has been measured.
Gene: Protein-coding gene on chromosome 2 (33,532,744 to 33,599,347, reverse strand). Ensembl gene ENSG00000119812.
Subcellular location (Human Protein Atlas): Vesicles
Gene Ontology:
Molecular function: protein binding; protein methyltransferase activity; RNA binding
Biological process: lysosome localization; positive regulation of ruffle assembly; tRNA splicing, via endonucleolytic cleavage and ligation
Cellular component: cytoplasm; nucleus; tRNA-splicing ligase complex
Genetic constraint (gnomAD): Loss-of-function variants: 22 observed, 48.71 expected, observed/expected ratio (o/e) 0.45, 90% interval 0.32 to 0.64. The upper end of that interval is the gene's LOEUF score, 0.64, which puts it in group 2 of 6, group 1 being the genes least tolerant of losing a copy. Missense variants: 535 observed, 548.56 expected, observed/expected ratio (o/e) 0.98, 90% interval 0.91 to 1.05. Synonymous variants: 211 observed, 194.46 expected, observed/expected ratio (o/e) 1.09, 90% interval 0.97 to 1.22.
Homologues: Orthologues: chimpanzee FAM98A (99% identical), macaque FAM98A (99% identical), dog FAM98A (98% identical), rabbit FAM98A (98% identical), pig FAM98A (98% identical), guinea pig FAM98A (97% identical), rat Fam98a (95% identical), mouse Fam98a (95% identical), zebrafish fam98a (71% identical), Drosophila melanogaster CG5913 (34% identical), Caenorhabditis elegans tag-322 (19% identical). Paralogues in human: TSLIG3B (48% identical), TSLIG3C (26% identical).
Diseases named in the same sentence as TSLIG3A in open-access papers:
TSLIG3A is named in the same sentence as 17 diseases in open-access papers, as found by Europe PMC text mining. Sharing a sentence is not in itself a finding about the gene and the disease.
TSLIG3A shares sentences with these, for which no sentence is quoted: breast carcinoma (4 papers); cancer (4); colorectal cancer (3); endometrial carcinoma (3); non-small cell lung carcinoma (2); tumor (2); endothelial dysfunction (1); Hypertension (1); infection (1); leukemia (1); liver cancer (1); medulloblastoma (1); osteopetrosis (1); ovarian carcinoma (1); postmenopausal osteoporosis (1); sarcoma (1); Stroke (1).